CRP (C-reactive protein)
Diseases named in the same sentence as CRP in open-access papers (continued):
Sharing a sentence is not in itself a finding about the gene and the disease.
Hypertension (2,555 papers, 2004 to 2026). The presence of chronic increased pressure in the systemic arterial system. "The univariate and multivariate regression analyses revealed that age, C-reactive protein, hypertension, serum uric acid level, and UAR are independent risk factors for POAF." (PMID 41705526, 2026). "The association between chronic pain and risk of hypertension was significantly mediated by CRP and depression (RDS-4 score); each mediating between 0.4% and 11.3% of the association." (PMID 41243808, 2026). "Together, depression (11.3%) and inflammation (0.4%), as measured by C-reactive protein, mediated 11.7% of the association between chronic pain and hypertension." (PMID 41243808, 2026). "In the Female Health Study, higher levels of CRP were associated with incident hypertension in females aged 45 years or older." (PMID 40864980, 2025). "CRP testing can be used for additional risk stratification in individuals already identified with one abnormal system (e.g., isolated hypertension or low HDL-C) to identify those with cumulative, multisystem dysregulation who are at the highest risk." (PMID 41295355, 2025). "A recent study has highlighted rs1205 gene polymorphism for the CRP gene, which is associated with increased plasma CRP levels and is correlated with retinopathy and hypertension in T1D patients." (PMID 41010041, 2025). "They suggest that CRP and white blood cell counts are partially mediated by the association between periodontitis and hypertension." (PMID 40002786, 2025). "Multi-center data revealed AA AD patients had increased risk of ischemic heart disease, hypertension, and atherosclerosis than Caucasian Americans (CA) AD patients, along with elevated pro-inflammatory markers (CRP, ferritin, ESR, and eosinophils)." (PMID 41377993, 2025). "Future research should validate these mechanisms through longitudinal biomarker assessments, including cortisol and C-reactive protein, and investigate targeted interventions for depressive symptoms to reduce hypertension risk in populations exposed to ACEs." (PMID 40630415, 2025). "Delayed sleep initiation beyond this period induces circadian misalignment, which elevates cerebrovascular risk through hypertension induction and inflammatory cascade activation, evidenced by C-reactive protein elevation." (PMID 41010731, 2025). "According to the majority of clinical research, CRP is a stand-aloneindicator for predicting the risk of atherosclerosis, myocardial infarction, hypertension, and cardiovascular events." (PMID 40978613, 2025). "Persistent short and long sleep durations associated with higher risk of hypertension; short sleep associated with increased CRP levels." (PMID 39981486, 2025). "Among patients with hypertension, an association was observed between increasing hypertension severity and higher CRP levels (Spearman’s rho = 0.300; p = 0.022)." (PMID 40572711, 2025). "Measuring CRP levels can aid in the early detection of individuals at risk of developing hypertension and cardiovascular disease." (PMID 40330210, 2025). "We found strong correlations between hs-CRP, adiponectin, chemerin, and IL-18 with risk factors for cardiometabolic syndrome, including abdominal obesity, hypertension, low HDL, and poor overall cardiometabolic health." (PMID 39940942, 2025). "Participants with elevated AIP and hs-CRP levels exhibited a higher risk of cardiovascular disease across subgroups, including age, sex, education level, BMI, residence, and hypertension status." (PMID 40842496, 2025). "Another potential mechanism involves the reduction of inflammation associated with hypertension, as some studies showed a decrease in C-reactive protein (CRP) levels in participants on FMD." (PMID 40137116, 2025). "Other risk factors for AAC included age, CRP, hypertension, and sarcopenia alone, while vitamin D was identified as a protective factor." (PMID 41323996, 2025).
Hypertension (continued). "This study analyzed associations between C-reactive protein (CRP) quartiles (Q1-Q4) and nutritional risk across subgroups (smoking, hypertension, cerebrovascular disease, age) among 313 cases." (PMID 40630494, 2025). "Clinical studies demonstrate that levels of C-reactive protein and white blood cell counts mediate the association between periodontal disease and high blood pressure." (PMID 40572711, 2025). "High blood pressure, elevated C-reactive protein (CRP), and increased waist circumference are recognized risk factors and predictors of cardiovascular disorders." (PMID 40722664, 2025). "Our results are in agreement with some epidemiological investigations associating CRP levels with hypertension and type 2 hypertensive diabetes as an independent risk factor for screening hypertension." (PMID 39273236, 2024). "The results of NP can be combined into a multi-marker approach, including interleukin and CRP, to identify target organ damage caused by hypertension in the heart, kidney and brain, to help facilitate early diagnosis of hypertension-mediated organ damage." (PMID 38791032, 2024). "In some earlier animal models, CRP exacerbated the response of vascular remodeling to injury and end-organ damage caused by hypertension." (PMID 38791032, 2024). "A cross-sectional study of 270 HF patients found that baseline smoking (χ2 = 6.33), unmarried (χ2 = 12.0), hypertension (χ2 = 5.72), higher body mass index (d = 0.45), and physical fatigue (d = 0.25) were associated with higher C-reactive protein (CRP) levels." (PMID 38327496, 2024). "Increased serum levels of C-reactive protein (CRP) and interleukin-6 (IL-6) are associated with high blood pressure and an increased risk of hypertension." (PMID 38720047, 2024). "Dietary patterns linked to CRP have been identified as crucial risk factors for hypertension and metabolic syndrome." (PMID 38515520, 2024). "Elevated levels of CRP can heighten the risk of hypertension by reducing the expression and activation of nitric oxide synthase, increasing endothelin-1 synthesis, and impairing endothelial-dependent vasodilation." (PMID 38515520, 2024). "For instance, increased risk for hypertension, altered serum lipid levels, and elevated levels of the inflammation marker C-reactive protein (CRP) and serum urate levels were secondary to the deletion’s impact on adiposity." (PMID 39332410, 2024). "Elevated levels of DII and CRP are associated with an increased risk of developing hypertension and metabolic syndrome." (PMID 38515520, 2024). "Reduced TAPSE, abnormal rMSSD, LV diastolic dysfunction, impaired LV/RV-GLS and history of hypertension, high CRP were associated with the occurrence of ventricular arrhythmia in symptomatic post-COVID patients." (PMID 39148011, 2024). "Comorbid hypertension and depressive symptoms were considered to be associated with a higher risk of elevated C-reactive protein levels." (PMID 39611132, 2024). "Patients with hypertension often exhibit elevated levels of inflammatory markers, including C-reactive protein and IL-6, which have been linked to a higher risk of stroke." (PMID 39144717, 2024). "They discovered that elevated levels of hs-CRP and IL-6 were linked to a higher risk of hypertension." (PMID 38292866, 2024). "Age > 65 years, history of hypertension and higher levels of CRP and creatinine were associated with an increased risk of mechanical ventilation." (PMID 37015962, 2023). "Vascular inflammation has been linked with hypertension through CRP, directly decreasing the expression of eNOS." (PMID 38024366, 2023). "It has been considered that increased CRP levels are associated with future incident hypertension and arterial stiffness." (PMID 37525185, 2023). "An expanding body of evidence indicates that inflammation has a major role to play in the development of high BP; elevated levels of CRP have been shown to be associated with the incidence of hypertension in middle‐aged adults." (PMID 37008812, 2023).
Hypertension (continued). "In contrast, there was a significant reduction in CV events when SB was decreasing after adjustment for age, sex, CV risk factors (family history, hypertension, dyslipidemia, type 2 diabetes and smoking), triglycerides and CRP." (PMID 37351092, 2023). "The association between CRP levels and QTc prolongation has been reported in patients with systemic inflammation or hypertension." (PMID 37252112, 2023). "This would demonstrate the importance of CRP as a predictor of cardiovascular risk factors, including hypertension and ischemic heart disease." (PMID 37008812, 2023). "With increasing age, hyperglycemia, higher aortic blood pressure, brachial blood pressure, and inflammation often damage vessels, and many studies have shown that cfPWV values are positively associated with DM, hypertension, age, and CRP." (PMID 36983652, 2023). "Inflammation is closely associated with hypertension, as evidenced by recent animal studies demonstrating elevated plasma levels of proinflammatory cytokines, including C-reactive protein (CRP), interleukin (IL)-6, IL-1β, and TNF-α, in hypertensive animals." (PMID 37795376, 2023). "Previous studies have demonstrated the association of chronic inflammation with hypertension and its complications and on CRP’s mediating role in the relationship between BMI and hypertension." (PMID 37238705, 2023). "High EAT volume was more common in men and associated with higher BMI, hypertension, increased left ventricular mass index (LVMi), C-reactive protein (CRP) and positive remodelling (all p < 0.05)." (PMID 38173787, 2023). "Since CRP is known to be associated with hypertension, which, in the long run, leads to HHD, we explored the association between CRP and HHD." (PMID 37298077, 2023). "In this model, the development of IMT thickening is significantly influencedby gender, the number of risk factors, smoking, hypertension,It score, and CRP level (p is 0.038; 0.046;0.013; 0.028; 0.05; 0.05, respectively)." (PMID 37814624, 2023). "Association between albumin (g/dL) and C-reactive protein (mg/L), stratified by sex, race/ethnicity, smoking and high blood pressure." (PMID 37653773, 2023). "Recent animal studies have shown that hypertension is associated with elevated plasma levels of proinflammatory cytokines, such as C-reactive protein (CRP), interleukin (IL)-6, IL-1β, and tumor necrosis factor (TNF)-α." (PMID 35445013, 2022). "The prognostic value of miR-505 in hypertension-associated inflammation is further supported by the clinical findings showing that the plasma level of miR-505 is positively correlated with that of CRP as well as SBP." (PMID 35571179, 2022). "In general, CRP levels are high in many African countries or in African Americans, especially in association with diabetes, hypertension, or infectious diseases." (PMID 35256885, 2022). "Our study is one of the studies that support the evidence that the combined effect of elevated-CRP levels and hypertension can potentially increase the risk of stroke in the middle-aged and geriatric Chinese population." (PMID 36262245, 2022). "Multivariable Cox proportional hazards regression models were used to estimate hazard ratios (HRs) with a 95% confidence interval (95%CI) of new-onset stroke risk according to elevated-CRP level and hypertension." (PMID 36262245, 2022). "When a seemingly healthy patient exhibits a high LDL level in addition to having hypertension and an increased CRP, there is an increased risk of myocardial infarction and stroke." (PMID 35627363, 2022). "IL-6 is a key regulator of the hepatic synthesis of acute phaseproteins including C-reactive protein (CRP) which has been linked to hypertension and cardiovascular disease." (PMID 37323554, 2022). "Recent studies indicate the prediction model that can identify patients at high risk of respiratory failure at an early stage using the CRP, hypertension, age, neutrophil and lymphocyte (CHANeL) predictors." (PMID 36441688, 2022).
Hypertension (continued). "People with the coexistence of elevated-CRP levels and hypertension had the highest risk of new-onset stroke among all subgroup analyses." (PMID 36262245, 2022). "Natsuko revealed that ALPK1 mRNA expression is associated with hypertension and creatinine, uric acid (hyperuricemia), and C-reactive protein levels, also supporting the role of ALPK1 in triggering gout." (PMID 36139553, 2022). "Clinical studies indicate that elevated CRP levels at baseline are more likely due to an increased risk of hypertension." (PMID 36703963, 2022). "CRP release is associated with conditions such as hypertension, obesity, cardiovascular disease, and ARDS, or infections with influenza viruses such as H1N1, MERS, and SARS-CoV-2." (PMID 35256885, 2022). "Apparently, the elevated CRP levels has been shown to be associated with many diseases such as cardiovascular disease, type 2 Diabetes, hypertension and neurodegenerative disorders." (PMID 35570546, 2022). "Meanwhile, the CRP level is associated with insulin resistance, hypertension, high-density cholesterol, triglycerides, and vascular endothelial dysfunction." (PMID 36556970, 2022). "Our findings indicate that the combined effect of elevated-CRP levels and hypertension increase the risk of new-onset stroke among the middle-aged and geriatric Chinese population." (PMID 36262245, 2022). "Studies have confirmed that inflammation is involved in the development of hypertension and that the inflammatory marker C-reactive protein(CRP) is significantly associated with hypertension." (PMID 36418968, 2022). "Based on these studies, we conducted our study to assess the combined effect of elevated-CRP levels and hypertension on the overall risk of stroke in the middle-aged and geriatric Chinese population." (PMID 36262245, 2022). "Few studies have evaluated the combined effect of elevated-CRP levels and hypertension on the risk of new-onset stroke in the general population." (PMID 36262245, 2022). "The association of high CRP and hypertension with stroke sub-type (hemorrhage and infarction) will be further investigated in future studies." (PMID 36262245, 2022). "Multivariable regression analyses revealed that serum MPO levels and activities remained independently associated with plaque progression, in addition to smoking, hypertension and CRP levels (all P < 0.05)." (PMID 36404308, 2022). "The subgroup analyses proved that individuals with elevated-CRP levels and hypertension have the risk of new cases of stroke in all subgroups." (PMID 36262245, 2022). "Other investigators have confirmed that higher CRP levels are an independent risk factor for hypertension." (PMID 35627363, 2022). "The survival distributions of the four groups are significantly different (Log-rank test P < 0.001); individuals with elevated-CRP levels and hypertension (group 4) possessed a higher risk of new-onset stroke compared to those in the other groups." (PMID 36262245, 2022). "Duffey and Davy indicated that higher HBI scores were associated with a lower risk of hypertension and also lower levels of C-reactive protein, insulin, FBS, and cholesterol." (PMID 36660267, 2022). "Although women were older than men (64.4 ± 10.3 vs. 59.5 ± 11.4 years, P < 0.001), men had worse risk profiles including high blood pressure, more frequent smoking and elevated triglyceride and C-reactive protein." (PMID 34980251, 2022). "As indicated by the results of this study, hypertension and coronary heart disease were identified as risk factors for increased CRP levels in patients with AECOPD, consistent with the data reported in the current literature." (PMID 34537026, 2021). "Compared with the CRP low-risk group, participants in the hs-CRP high-risk group had a 36.4% higher risk of hypertension after adjustment for all covariates (hazard ratio: 1.364, 95% CI: 1.006–1.849; p = 0.03)." (PMID 34925916, 2021).
Hypertension (continued). "A nested case–control study of 400 normotensive women indicated that the risk of developing hypertension during follow-up increases with higher quartiles of IL-6 and C-reactive protein." (PMID 34698811, 2021). "Age ≥ 70 years, SpO2 < 97%, thrombocytopenia, creatinine level, CRP elevation > 1.5 mg/dL, cardiovascular disease, and hypertension were associated with an increased risk for O2 support." (PMID 34899724, 2021). "Low-grade and persistent inflammation contribute to progression of experimental and clinical hypertension; C-reactive protein levels are associated with deterioration of hypertension, suggesting that hypertension is in part an inflammatory disorder." (PMID 33815099, 2021). "GOLD class (adjusted OR 1.5; 95% CI 1.002–2.236), a current smoking status (adjusted OR 2.1; 95% CI 1.109–4.361), and hypertension (adjusted OR 1.65; 95% CI 1.019–2.683) were also significantly associated with CRP level." (PMID 34537026, 2021). "Uric acid has also been linked to an increased risk of hypertension, further complicating the relationship between uric acid, CRP, hypertension, renal function, and metabolic syndrome." (PMID 34063875, 2021). "In conclusion, this study revealed a weak positive association between CRP levels and future incidence of hypertension in the Chinese population." (PMID 34925916, 2021). "For cfPWV, there were significant univariate associations with age, MAP, hypertension, C-reactive protein (CRP) and inverse associations with eGFR and male sex." (PMID 34957246, 2021). "The incidences of hypertension in hs-CRP, low-risk, average-risk, and high-risk groups were 17.6% (200/1135), 25.9% (521/2015), and 29.7% (191/644), respectively." (PMID 34925916, 2021). "Prospective studies have further shown that baseline levels of CRP are significantly associated with the incidence of hypertension among normotensive individuals, and with hypertension remission among hypertensive patients." (PMID 34943129, 2021). "A definite association between hypertension and low cognitive function was represented in those with high hs-CRP levels, with an OR of 7.68 (95% CI, 1.66 to 35.59)." (PMID 34293257, 2021). "In the logistic regression analysis, the three parameters were associated with an increased risk of MS after adjustment for age, sex, hypertension, DM, dyslipidemia, smoking, alcohol intake, and C-reactive protein." (PMID 34403431, 2021). "On the other hand, a high intake of saturated fats, added sugars, and simple carbohydrates have been linked to increased inflammatory markers (CRP/high sensitivity (hs)-CRP, IL-6) and risk of hypertension and cardiovascular disease." (PMID 33806342, 2021). "Increased BMI has been shown to be associated with higher serum CRP levels whilst increased CRP levels have been found to be associated with medical conditions such as hypertension and type 2 diabetes." (PMID 33517931, 2021). "History of hypertension, leukocytosis and elevated CRP concentrations were associated with higher odds of coagulopathy." (PMID 33564286, 2021). "One meta-analysis showed a significant association between hs-CRP and the development of hypertension (relative risk [RR] = 1.72, 95% CI: 1.38–2.07), as observed in a US population-based study, but not in Asian populations (RR = 1.03, 95% CI: 0.95–1.12)." (PMID 34925916, 2021). "Meanwhile, based on clinical practice, the conventional risk factors are prioritized; the marginal benefit of including hs-CRP in risk stratification for hypertension in this study was attenuated (p > 0.05)." (PMID 34925916, 2021). "In the univariate analysis, age, male sex, BVAS score, hypertension, interstitial lung disease, CRP, and NFI at diagnosis ≥1.24, were significantly associated with all-cause mortality." (PMID 33852653, 2021). "Our results show a weak positive association between CRP levels and future incidence of hypertension in apparently healthy, normotensive Chinese adults." (PMID 34925916, 2021).